RN7SL451P (RNA, 7SL, cytoplasmic 451, pseudogene)
Gene: Miscellaneous RNA gene on chromosome 1 (8,979,576 to 8,979,874, reverse strand). Ensembl gene ENSG00000265141.
Homologues: Orthologues: chimpanzee Metazoa_SRP (99% identical), macaque Metazoa_SRP (91% identical), guinea pig Metazoa_SRP (63% identical). Paralogues in human: RN7SL1 (85% identical), RN7SL2 (85% identical), RN7SL3 (84% identical), RN7SL44P (83% identical), RN7SL769P (83% identical), RN7SL478P (83% identical), RN7SL664P (83% identical), RN7SL300P (82% identical), RN7SL15P (82% identical), RN7SL804P (82% identical), RN7SL45P (82% identical), RN7SL797P (82% identical), and 705 more.